MTOR (mechanistic target of rapamycin kinase)
Diseases named in the same sentence as MTOR in open-access papers (continued):
Sharing a sentence is not in itself a finding about the gene and the disease.
tumor (continued). "However, some of the drugs acting on these pathways (including the mTOR inhibitor Rapamycin) are active in mice only during therapy, with recovery of tumor growth after treatment suspension." (PMID 31739524, 2019). "Adding to recently published results that suggest therapeutic potential for PI3K/mTOR inhibition in TfRCC, our work shows dual mTORC1/2 inhibition suppresses the Akt/mTOR pathway and tumor growth in TfRCC preclinical models more effectively than selective mTORC1 inhibition." (PMID 31519159, 2019). "Nonetheless, regardless of the specific resistance mechanism, our results clearly show that the patient-derived tumor cells are ‘oncogene addicted’ to PI3K/mTOR activation and therefore inhibition of this pathway is sufficient to overcome cetuximab resistance in this patient." (PMID 31653970, 2019). "In this study, our results demonstrate that brevilin A suppresses PI3K/AKT/mTOR activity in CNE-2 cells and in in vivo CNE-2 tumor xenografts, which may be associated with inhibition of NPC cell proliferation and induction of apoptosis." (PMID 31178739, 2019). "Hence, we checked the molecular interaction between tumor-associated proteins such as AKT, PI3K, mTOR, and cell cycle regulating proteins such as CHK1, CHK2, CDK6, Cyclin D1, and proteins from MAPK signaling including MEK1, p38MAPK, and SAPK/JNK." (PMID 31783627, 2019). "This is the first report to show that kindlin-2 could promote VEGFA secretion through the mTOR pathway and that this signalling pathway connects tumour cells with vascular endothelial cells." (PMID 31427543, 2019). "DTLL's tailored internalization into tumor parenchyma cells after specifically binding to EGFR/HER2 might contribute to blockage of their targeting pathways—the PI3K/AKT/mTOR signaling and PD‐L1‐medicated tumor escape from immunosurveillance." (PMID 30681288, 2019). "Data emanating from western blots performed on proteins extracted from tumor sections and assessing the effect of the different treatments on the expression of mTOR and its phosphorylated form p-mTOR, showed different levels of inhibition in the diabetic and non-diabetic animals." (PMID 30863490, 2019). "Thus, we inspected the involvement of the potential downstream effector mTOR in MAP3K7-modulated tumor malignancy in HCC cells." (PMID 31214512, 2019). "Therefore, in this study, we focus on the relationship between the expression level of signaling factors in PI3K/AKT/mTOR pathway and recurrence tumor from HNSCC patients." (PMID 31756179, 2019). "In addition, the combinatorial administration significantly suppresses the infiltration of tumor cells by decreasing the activation of Notch/AKT/mTOR signaling pathway and down-regulating the expression of angiogenesis-associated proteins, HIF1α and VEGF." (PMID 31878360, 2019). "Since the activation of mTOR has been shown to contribute to tumour progression, it can be speculated that the honokiol-induced inhibition of cell proliferation in HNSCC cells is mediated through the downregulation of EGFR/mTOR signalling pathway." (PMID 31877856, 2019). "PI3K/Akt/mTOR pathway is closely related to the tumorigenesis and progression of BC and plays a critical role in the apoptosis, survival and cell‐cycle of tumor cells." (PMID 30907072, 2019). "Moreover, rapamycin significantly reduces tumor growth, splenomegaly and metastasis of B cell lymphoma through theinhibition of the Lyn-activated mTOR pathway." (PMID 30873380, 2019). "Although challenged by some previous reports, mTOR overexpression in the tumour edge would be expected since tumour expansion is classically considered centrifugal and epithelial to mesenchymal transition occurs primarily in the tumour edge." (PMID 30650598, 2019).
tumor (continued). "In this study, we evaluated whether formononetin can inhibit tumor growth by suppressing the mTOR pathway and whether it can enhance the efficacy of everolimus." (PMID 31007702, 2019). "Moreover, in PI3K inhibitor-resistant squamous cell carcinoma, AXL binds to EGFR and activates the PLCα/PKC/mTOR signalling pathway to maintain tumour progression." (PMID 31684958, 2019). "Interestingly, BSN inhibited not only constitutive but also inducible PI3K/Akt/mTOR/p70S6K/4E-BP1 phosphorylation in tumor cells." (PMID 31013639, 2019). "However, it has been reported that tumours develop resistance to alpelisib by activation of the mTOR pathway." (PMID 31492956, 2019). "Additionally, miR-19, a member of the miR-17-92 cluster, downregulates expression of the tumor-suppressor phosphatase and tensin homolog (PTEN), thereby activating the protein kinase B (AKT)/mammalian target of rapamycin (mTOR) pathway in tumor cells." (PMID 30987065, 2019). "We hypothesized that targeting both the microtubule cytoskeleton and the PI3K/AKT/mTOR pathway would lead to a synergistic anti-tumor effect." (PMID 31703728, 2019). "The results of our study indicate that disorders in the mTOR system may occur as early events in PCa later replaced by its decrease after tumor progression." (PMID 31885728, 2019). "Tumor cells can be resistant to ROS through mTOR-mediated antioxidant defense." (PMID 31929797, 2019). "Therefore, the oxygen levels in the tumor microenvironment should be considered in the regulation of antioxidant defense through mTOR inhibition in solid tumors." (PMID 31929797, 2019). "In vitro experimental evidence indicated that the inhibition of aberrant angiogenesis elicited by local or systemic administration of Sema3F in vivo may be mediated by the NRP2-dependent inhibition of VEGF production and Akt-mTOR signaling in tumor cells." (PMID 31052281, 2019). "Anti-tumor agent rapamycin and its derivatives induce autophagy by inhibiting the mTOR pathway." (PMID 31409760, 2019). "In particular, clinically targeting mTOR signaling during radiotherapy could increase tumor radiosensitivity." (PMID 31929797, 2019). "Therefore, targeting both the microtubule cytoskeleton and the PI3K/AKT/mTOR pathway can lead to a synergistic anti-tumor effect." (PMID 31480338, 2019). "PTEN functions as tumor suppressor by inhibiting PI3K/AKT/mTOR-mediated cell survival pathway." (PMID 31200745, 2019). "Inhibiting ROR1 with small molecules and monoclonal antibodies, or inhibiting the key regulators involved in AKT/mTOR signaling could effectively increase the sensitivity of tumor cells to erlotinib." (PMID 31452776, 2019). "From these data, we infer that MACC1 regulates PDL1 expression and tumor immunity through the c‐Met/AKT/mTOR pathway in GC cells and suggest that MACC1 may be a therapeutic target for GC immunotherapy." (PMID 31557409, 2019). "Abnormal expression of mTOR leads to conditions such as diabetes and tumor development." (PMID 31007702, 2019). "Histological tumour differentiation and microvascular invasion were not linked with p-mTOR overexpression and therefore these histological features per se should not motivate the prescription of mTOR inhibitor-based immunosuppression in clinical practice." (PMID 30650598, 2019). "Dual PI3K/mTOR inhibitors like BEZ235 showed anti-tumor effects in HNSCC cell lines and tumorgrafts with PIK3CA mutations, its efficacy in HNSCC patients remained unknown." (PMID 30754640, 2019). "Indeed, preclinical studies showed the ability of mTOR inhibition to reduce the number of lytic bone metastases and to increase bone mass in tumor-bearing mice." (PMID 31766386, 2019). "We next investigated whether BSN modulated PI3K/Akt/mTOR/p70S6K/4E-BP1 phosphorylation in tumor cells." (PMID 31013639, 2019).
tumor (continued). "In the present study, the mTOR pathway was upregulated in the explanted liver of a significant proportion of patients with HCC undergoing LT and this finding was associated with increased tumour recurrence rates." (PMID 30650598, 2019). "This maternal diet effect led to an improvement of food intake, associated with the maintenance of muscle protein synthesis and degradation by modulating the activity of proteolysis pathways and preserving mTOR pathway in skeletal muscle in adult offspring tumour-bearing rats." (PMID 31200474, 2019). "In this review, the effects of mTOR inhibition on tumor radiosensitivity were discussed." (PMID 31929797, 2019). "PI3K/AKT/mTOR pathway favors tumor growth and cell size over proliferation and regulates autophagy." (PMID 31857847, 2019). "Triplet joint therapy of Ribociclib with exemestane and Everolimus (mTOR inhibitor), or Letrozole and Alpelisib (PI3Ka-selective inhibitor) were investigated in HR+ ABC patients whose tumor cells endured PI3K/AKT/mTOR and/or cyclin D-CDK4/6-p16-Rb pathway alterations." (PMID 31777590, 2019). "At the same time, a good deal of preclinical evidence suggests that simultaneously mTOR inhibition along with autophagy suppression could boost cytotoxicity in tumor cells." (PMID 31557936, 2019). "It has also been shown that 4E-BP1 may regulate tumor initiation and progression through mTOR signaling in PCa." (PMID 30761182, 2019). "Therefore, exploitation of both the kinase domain as well as FRB domain of mTOR should potentially inhibit mTOR-related dysfunctions in the context of tumor growth." (PMID 30609721, 2019). "When exposed to a nutrient-poor and hypoxic environment, however, tumor cells could benefit from metabolic changes induced by mTOR inhibitors that would ultimately enable them to better economize resources." (PMID 31510109, 2019). "Our results show that autophagy mostly acts as a survival mechanism and that depletion of HIF-2α expression, either alone or in combination with autophagy and mTOR inhibition, greatly enhances cell death and induces tumor remission, demonstrating the reliance upon HIF-2α expression for survival." (PMID 31151160, 2019). "Rapamycin is a popular mTOR inhibitor applied among human tumor cases." (PMID 31193204, 2019). "Hence, in pre-clinical studies, dual PI3K/mTOR inhibitors are more effective at promoting tumor cell death, as expected." (PMID 31817676, 2019). "Moreover, the targetable signalling pathways IGF1R, NOTCH and mTOR were upregulated in AFP-high tumours." (PMID 31285588, 2019). "Furthermore, PD-L1 expressed in tumor cells promotes glycolysis via activation of the AKT/mTOR pathway." (PMID 31468283, 2019). "Here, immunohistochemistry (IHC) results showed the weakest staining of phosphorylated mTOR (p-mTOR) and phosphorylated S6 ribosomal protein (p-S6), two important activated proteins of mTOR signalling, in the tumour tissues of the group receiving the combination of verteporfin and 5-Fu or DOX." (PMID 31337986, 2019). "Moreover, we showed that JPH203 was effective in suppressing tumor proliferation via mTOR signaling by cell-based studies and a mouse xenograft model." (PMID 31601917, 2019). "We have shown previously that prolonged incubation of several tumor cell lines with the dual PI3K/mTOR-inhibitor PI-103 leads to a re-activation of p-Akt, which in turn might increase tumor cell growth and survival." (PMID 30943918, 2019). "It has been reported that AMPK/mTOR/p70S6K signaling pathway plays a role in tumor development." (PMID 31147451, 2019). "Tumor radioresistance is closely related to high levels of mTOR signaling in tumor tissues." (PMID 31929797, 2019). "Also mir-99a is a known tumor suppressor that controls cell proliferation by inhibition of AKT/mTOR signaling." (PMID 31208318, 2019).
tumor (continued). "It is has been widely reported that PI3K/AKT signaling pathway regulates EMT by promoting the phosphorylation of downstream target proteins (Bad, Caspase9, NF‐κB, GSK‐3β, mTOR, p21Cip1, p27 Kip1, etc.)to further mediates tumor proliferation, invasion and metastases 46-48." (PMID 31410208, 2019). "PI3K/AKT/mTOR activation promotes tumor development as drug resistance." (PMID 31632198, 2019). "Considering that diffuse-type GC-initiating cells were more resistant to anti-tumor drugs than intestinal-type cells or established GC cell lines, these results indicate that mTOR inhibitors may be useful for the treatment of diffuse-type GC-initiating cells." (PMID 30866995, 2019). "Alternatively, patient-derived tumor grafts may be transplanted to animals, followed by testing their response to mTOR inhibitors." (PMID 31277692, 2019). "These include the widely used carcinogens DMBA-TPA and 4-nitroquinoline-1-oxide (4NQO), which have both been reported to result in persistent mTOR activation, leading to tumour development, and regression is observed after the administration of the mTOR inhibitor rapamycin." (PMID 30970654, 2019). "Then, the in vivo experiment also confirmed that Mfn2 could inhibit the tumor growth, and depress the Cyclin D1, Ras, Myc, NF-κB p65, Erk1/2 and mTOR protein expression." (PMID 31384172, 2019). "mTOR inhibition in the tumor may also have consequences that allow T cells to enhance their anti-tumor recognition." (PMID 31817676, 2019). "Patients receiving single-agent prednisone (≤10 mg/day) at CPI initiation seemed to have numerically higher tumor responses to CPI therapy than those receiving single-agent mTOR inhibitors, calcineurin, or combination immunosuppressant therapy (63% compared with 42%)." (PMID 30992053, 2019). "Meta-analyses indicate that mTOR blockade reduces the incidence of several neoplasia." (PMID 31174250, 2019). "mTOR inhibition has indeed been shown to enhance cell proliferation in pancreatic tumour regions that are poorly vascularized, while inhibiting proliferation at tumour margins." (PMID 30967004, 2019). "In this study, we first found that down-the regulation of PBF inhibited AKT/mTOR and Wnt/β-catenin pathways, both of which might play important roles in tumor-related phenotypes." (PMID 31637306, 2019). "Interestingly, mTOR signaling has been reported to induce hypermethylation of different tumor suppressor genes including PTEN via upregulating DNA methyltransferases." (PMID 31637215, 2019). "Taken together, the antiangiogenesis effect of TMEA may be mediated via VEGF/PI3K/AKT/mTOR signaling pathway to further inhibit tumor growth." (PMID 32047442, 2019). "This case series adds to the existing evidence that everolimus has anti-tumor activity in ATC, and responses may correlate with mutations along the PI3K/mTOR axis." (PMID 30863722, 2019). "Gene expression levels measured relative to the adjacent normal cortex sample revealed numerous oncogenic driver genes with >2-fold higher expression in the tumour and clone samples, including genes encoding AURKA/B, CDK4/6, FGFR1, AKT1/2, MTOR, MET, PIK3C2A, WNT5A, SFRP4, and MYC." (PMID 30736342, 2019). "In addition, PI3K subunit p85α and AKT1/2 were overexpressed, particularly in advanced tumor stages, and the phosphorylation level of mTOR and S6K1 was increased in CRC." (PMID 30754640, 2019). "The PI3K/Akt/mTOR signaling pathway is frequently hyperactivated in most human cancers, and inactivation of tumor suppressors such as PTEN, LKB1, and TSC1/2, which antagonize the PI3K/AKT/mTORC1 pathway, may drive tumorigenesis." (PMID 30761182, 2019).
tumor (continued). "The switch towards the senescence-associated secretory phenotype (SASP) of tumor cells is activated by mTOR signaling and promotes non-cell-autonomous resistance." (PMID 30927928, 2019). "As in other tumor entities, a rational subgroup selection and combination or a sequence treatment algorithm might be the key for the successful employment of mTOR inhibitors in GB treatment." (PMID 31510109, 2019). "Globally, genes in post-NAC samples were involved in pathways associated with actionable targets in tumor treatment where, beside the canonical PI3K/Akt/mTOR, EGFR, and Ras signaling pathways the most represented terms were related to regulation of cell cycle processes." (PMID 31717320, 2019). "Furthermore, FLI using green fluorescent protein has been employed to study the anti-tumor effect of the mTOR inhibitor rapamycin in EC models with different PTEN expression levels." (PMID 31783595, 2019). "Although ligustrazine and ferulic acid suppressed PTGS2 and MTOR in tumor or nervous system diseases, the cooperation of ligustrazine, ferulic acid, and tetrahydropalmatine is unknown whether or not via PTGS2 or MTOR, in spite of their valid effect in EMS." (PMID 31781263, 2019). "PD-L1 represses tumor autophagy and enhances the mTOR pathway in both ovarian cancer and melanoma." (PMID 31824865, 2019). "Furthermore, leelamine has been shown to target key oncogenic pathways (RTK–AKT/STAT3/MAPK, AKT/mTOR) in various tumor cells." (PMID 31330969, 2019). "Unfortunately, resistance towards mTOR inhibitors develops and the tumor becomes reactivated." (PMID 31010254, 2019). "Blocking PI3K/Akt/mTOR pathway and inhibit cell proliferation and tumor growth." (PMID 31134198, 2019). "It is known that the PI3K/Akt/mTOR pathway plays a critical role in the proliferation, apoptosis, and metastasis of tumor development, the PtoxPdp might be through similar pathway." (PMID 31557166, 2019). "Interestingly, metformin, a drug widely used in the treatment of type 2 diabetes mellitus and polycystic ovary syndrome, seems to possess anti-tumor properties via indirect mTOR protein inhibition." (PMID 31331108, 2019). "This approach may be the mainstay of new combinations of treatments, with additional agents targeting components of other pathways (e.g., PI3K, AKT, mTOR, or TGFβ), including immune system effectors of the tumor microenvironment." (PMID 31652660, 2019). "MTOR inhibitors that could block the catalytic activity of mTOR could more effectively inhibit mTOR functions and may have better anti-tumor activity." (PMID 31817676, 2019). "Furthermore, a heterotypic tumour-stromal distribution of MAPK and mTOR pathways was also observed in ‘Null’ signature PAC tumours." (PMID 31772293, 2019). "Likewise, T cells conditioned in vitro with MDSCs show an increased anti-tumour activity after adoptive T cell based immunotherapy, which is associated with increased IFN-γ expression and diminished mTOR signalling." (PMID 31142770, 2019). "Preclinical and clinical studies showed that PI3K/AKT/mTOR pathway inhibition has a synergistic effect with endocrine therapies, and could reduce tumor progression in HR+ PI3K mutant BCs beyond the first endocrine line of treatment." (PMID 31450618, 2019). "Although enhanced mTOR signaling activation has been reported to not be associated with the survival of some tumor patients, targeting mTOR signaling is still a reasonable approach for tumor radiotherapy." (PMID 31929797, 2019). "Besides promoting tumor cell proliferation and survival, the Akt/mTOR pathway is recognized as a major pathway regulating autophagy, and inhibitors of the Akt/mTOR axis, such as rapamycin analogues, can intensify the autophagic process." (PMID 30943918, 2019). "Indeed, the PI3K/AKT/mTOR pathway is frequently hyper-activated in tumor cells and also plays an important role in cancer metastasis." (PMID 31507423, 2019). "Tumor growth has been shown to be regulated through the mTOR pathway." (PMID 31007702, 2019).